IL1B (interleukin 1 beta)
Diseases named in the same sentence as IL1B in open-access papers (continued):
Sharing a sentence is not in itself a finding about the gene and the disease.
lung carcinoma (continued). "As these patients were extensively screened prior to recruitment, the indication is that inhibition of IL-1β reduced the progression, invasiveness and metastatic spread of early stage lung cancers that were undiagnosed at time of recruitment." (PMID 31231372, 2019). "Anti-inflammatory therapy targeting the IL-1β innate immunity pathway can significantly reduce incident lung cancer and lung cancer mortality." (PMID 31174565, 2019). "Herein, we compared the effects of mPGES-1 inhibitor Compound III (CIII) with the cyclooxygenase (COX)-2 inhibitor NS-398 on protein and lipid profiles in interleukin (IL)-1β-induced A549 lung cancer cells using mass spectrometry." (PMID 31231223, 2019). "This study alone suggests the potential role of IL-1β inhibition as a promising strategy for the treatment of lung cancer." (PMID 31438559, 2019). "The CANTOS trial has opened the door to the human relevance of the relationship between IL-1β signaling and lung cancer and provides promising avenue with which to explore new anti-cancer therapies." (PMID 30832375, 2019). "Of note, exploratory data from a large randomized trial has provided evidence that in subjects with high CRP, yet otherwise healthy, inhibition of IL-1β by canakinumab, reduced the incidence of lung cancer, as well as the lung cancer related mortality." (PMID 30365491, 2018). "We showed that baseline undetectable IL-1b is an independent significant prognostic factor of survival in lung cancer patients treated with radiotherapy." (PMID 29398577, 2018). "In animal models of lung cancer, bortezomib and IKKβ inhibitors caused resistance or paradoxical tumor promotion via development of secondary mutations, NF-κB inhibition in myeloid cells, or enhanced IL-1β secretion by tumor-associated neutrophils through an unknown mechanism." (PMID 29445180, 2018). "We next used a specific siRNA to interfere with RUNXOR expression and detected the RUNX1 expression in both MDSCs from the tumor tissue of lung cancer patients and MDSCs induced from healthy donor PBMCs with GM-CSF + IL-1β." (PMID 29914443, 2018). "Human MDSCs used in this study were isolated from tumor tissue of patients with lung cancer by FCM or induced from PBMCs of healthy donors with IL-1β + GM-CSF." (PMID 29914443, 2018). "In association with elevated USP17 expression, the levels of inflammatory mediators, including IL-1β, IL-6, and IL-8 were increased in lung cancer samples." (PMID 30038267, 2018). "Clinical treatment reduced IL-1β levels of lung would have an opportunity to improve inflammation and the development of lung cancer." (PMID 29254155, 2017). "NLRP3 inflammasome components IL-1β and IL-18 were found to be highly expressed in lung cancer cell lines and tissues than in cancer-adjacent normal tissues." (PMID 28865486, 2017). "We found that TAMs are another source of IL-1α and IL-1β release in lung cancer lesions in tumor-bearing mice." (PMID 27528423, 2016). "Interleukin (IL)‐1β was used in this study to stimulate CCL20 production from lung cancer cells and activate signalling pathways of MAPK and PI3K." (PMID 26968871, 2016). "For instance, recent data reveal that DNA methylation is frequent in promoter regions of IL-1b, IL-6 and IL-8 in lung cancer." (PMID 25590298, 2015). "TNFα induces IL-8 and IL-1β synthesis and secretion from adenocarcinoma lung cancer cells, Calu-3 cells." (PMID 26594334, 2015). "For this, we treated A549 lung cancer cells with TNFα, IL1β, E. coli lipopolysaccharide (LPS), as well as IFNγ, and assessed secretion of the cytokines CXCL10, IL6 and IL8." (PMID 26030458, 2015). "PBMC gene expression of CCL3, IL8 and IL1β was higher in lung cancer patients compared to the same patients at each of four sequential timepoints after removal of their tumors, while CXCL10 and IL2Rα were essentially unchanged." (PMID 23762239, 2013).
lung carcinoma (continued). "A key role for IL-1β-inducible IL-8 in the progression of lung cancer is strongly suggested by various clinical studies demonstrating that IL-8 detected in patient biopsy specimens positively correlates with tumor angiogenesis and metastasis." (PMID 18801189, 2008). "To evaluate whether inhibition of the IL-1β–IL-1R axis could prevent or treat lung cancer brain metastasis, we performed both prevention and treatment studies in mouse models." (PMID 41436606, 2025). "A retrospective study involving 463,679 individuals showed that exposure to air pollution can trigger IL-1β release, promoting mutation-driven lung cancer development in never-smokers." (PMID 40940992, 2025). "Additionally, anti-inflammatory therapy targeting IL-1β shows promise for patients with specific cancers, particularly lung cancer." (PMID 40079000, 2025). "The decrease in lung cancer mortality observed in the CANTOS trial suggests that IL-1β-directed therapies could benefit patients with specific types of cancer." (PMID 40079000, 2025). "In lung cancer, IL-1β is a key driver of inflammation in the tumor microenvironment, and its inhibition may enhance the efficacy of PD-1 inhibitors." (PMID 39927795, 2025). "Additionally, IL‐6 and IL‐8 promote angiogenesis in NSCLC by inducing VEGF expression, while long‐term exposure to IL‐1β induces a memory‐like epithelial–mesenchymal transition (EMT) phenotype in lung cancer tissues." (PMID 41223031, 2025). "Additional priming mechanisms may include the activation of receptor-interacting protein 1 (RIPK1) or the NF-κB pathway by radiation therapy, both leading to the production and secretion of IL-1β in lung cancer cell lines." (PMID 39858071, 2025). "Of note, in a large clinical trial, an IL-1β blocking antibody (canakinumab) significantly reduced the incidence of lung cancer and improved overall survival, suggesting a pro-tumorigenic role for IL-1β in lung cancer." (PMID 38391959, 2024). "Fascinatingly, in lung cancer, IL-1β expression has been related to lung cancer development, and its higher levels in serum or tumor tissue have been correlated with a poorer prognosis for lung cancer patients." (PMID 38103126, 2024). "It has also been reported that IL‐1β is involved in PD‐1 expression in lung cancer, suggesting that IL‐1β may be involved in the immune escape mechanism of malignant tumors." (PMID 38798075, 2024). "This can in part interpret our findings that the IL-1β SNP (rs16944) may be a protective factor by controlling the levels of IL-1β in lung cancer patients." (PMID 38103126, 2024). "Moreover, research has demonstrated a correlation between the occurrence and development of lung cancer and the concentration of IL-1β." (PMID 38317229, 2024). "Additionally, IL-1β has a substantial role in lung cancer development via regulation of tumor growth, invasiveness, and angiogenesis, which were demonstrated in a clinical study using the anti-IL-1β antibody canakinumab." (PMID 39336475, 2024). "Additionally, data from a clinical trial suggest that canakinumab, a therapeutic agent targeting the IL-1β innate immune pathway, holds significant potential in reducing both the incidence and mortality of lung cancer." (PMID 38317229, 2024). "Additionally, TNF-α, IL-6, and IL-1β induce elevated Ido1 expression in the context of immunosuppression in lung cancer progression." (PMID 39759510, 2024). "This possibility was supported by the finding of a significantly reduced incidence of lung cancer and decreased lung cancer mortality in a trial after the activity of the major product of inflammasome activation, IL‐1β, was inhibited by a specific antibody, canakinumab." (PMID 38336727, 2024). "In the current investigation, compared to a lung cancer control, chia seed oil and hydroethanolic extract significantly decreased the expression of IL-6 and IL-1β (by around 10.8 and 13.17% for ether extract and 4.25 and 11.20% for alcohol extract, respectively)." (PMID 39338293, 2024).
lung carcinoma (continued). "A few biological pollutants have been reported to promote lung cancer via inducing inflammatory cytokines secretion, such as IL-1β, IL-6, and TGF-β, as well as suppressing immunosurveillance by upregulating regulatory T (Treg) cells while dampening the function of CD8+ T cells and dendritic cells." (PMID 38542056, 2024). "Notably, elevated levels of IL-1β, IL-10, and TNF-α were linked to lung cancer risk only in the African American population." (PMID 38067398, 2023). "IL-6, IL-1β, and IFN-γ had consistent associations with the lung cancer risk (HR [95% CI]: 1.31 [1.04–1.66], 1.25 [1.06–1.48], 1.23 [1.07–1.42], respectively), whereas, in ever-smokers, only IL-6 had an association with the lung cancer risk (HR [95% CI]:1.38 [1.16–1.64])." (PMID 38067398, 2023). "Furthermore, IL-1β was found to be highly expressed in Kirsten rat sarcoma viral oncogene homolog (KRAS) -mutant lung cancer, IL-1β blockade demonstrated a transformative effect, switching the immune-suppressive TME to an anti-tumor immune state." (PMID 38066523, 2023). "Additionally, the study showed that IL-1β values in the serum were significantly higher in patients with lung cancer but of African American race." (PMID 37373987, 2023). "Moreover, the ROC plot analysis revealed that several inflammatory markers, including IL-1b, IL-2, IL-6, IL-10, IL-12p70, and TNF-alpha, are significantly associated with the risk of lung cancer." (PMID 37373957, 2023). "Special interactions between smoking duration, IL1B rs3136558 and POLR1G rs967591; smoking-duration, IL1B rs1143633, rs3136558 and rs1143630; and IL1B rs1143633, PPP1R13L rs1970764 and POLR1G rs735482 were observed in relation to lung cancer risk." (PMID 37147350, 2023). "Serum levels of IL-6, IL-1β, and IFN-γ were associated with lung cancer risk." (PMID 38067398, 2023). "Furthermore, the regression analysis demonstrated that patients with lung cancer had significantly higher odds for increased levels of IL-1b, IL-2, IL-6, and IL-12p70 above the calculated cut-off values." (PMID 37373957, 2023). "Similar to IL-1β, high levels of IL-6 may contribute to the growth, metastasis, and immune escape of lung cancer cells." (PMID 37033918, 2023). "PEL extracts regulated the IL-1β/miR-i101/Lin28B signaling pathway for lung cancer prevention." (PMID 36771198, 2023). "However, the change in IL-18 levels was very modest in lung epithelium compared with lung cancer cells, indicating a more profound role of IL-1β in lung epithelium-induced inflammation." (PMID 36694200, 2023). "STAT signaling is one of the most well-characterized modes of PD-L1 induction in cancer cells, therefore we tested whether IL-1β induces STAT activation in lung cancer cells." (PMID 37985999, 2023). "In this study, serum levels of IL-6, IL-1β, and IFN-γ were associated with lung cancer risk." (PMID 38067398, 2023). "An examination of the Cancer Genome Atlas database shows that for lung cancer, IL-1 and TNF reveal a tendency as an oncogene, as patients with higher IL-1β and TNF-α mRNA levels are linked to shorter overall survival, although this correlation does not reach statistical significance." (PMID 37259369, 2023). "One study showed that IL-1β induced signaling pathway can directly stimulate the production of CCL20 in lung cancer cells, and activate MAPK and PI3K signaling pathways through its autocrine, which has a positive effect on the progression and invasion of cancer cells in lung tissue." (PMID 36447119, 2023). "The human lung cancer cells require 100 times more of the mouse derived IL-1β to generate an IDO1/PD-L1 response that is seen with the human-derived IL-1β, indicating that further in vivo characterization needs to be performed in syngeneic or humanized mouse models." (PMID 37985999, 2023). "Notably, elevated serum levels of IL-1β, IL-10, and TNF-α were linked to lung cancer risk only in the African American population." (PMID 38067398, 2023).
lung carcinoma (continued). "Considering the important role of inflammatory conditions and IL-1β in the occurrence and development of lung cancer, we hope that the inhibition of IL-1β induced by these nanoparticles will open new avenues for cancer treatment by targeting lung tumor inflammation." (PMID 37304133, 2023). "Some studies have shown that the level of IL-1β is higher in patients with lung cancer." (PMID 36992837, 2023). "Overall, we propose that studies in GEMMs and humanized mice models should be employed to further delineate the mechanism of IL-1β in promoting lung cancer and to determine the efficacy of using IL-1 blockade therapies in combination with other treatments for lung adenocarcinoma." (PMID 37985999, 2023). "Since TDO2 was previously found to be upregulated concomitantly with IL-1β in normal lung cells, we asked whether IL-1β had the ability to regulate Trp-metabolizing enzymes in lung cancer cells." (PMID 37985999, 2023). "Therefore, in this study, we aimed to elucidate the mechanisms by which IL-1β and TonEBP affect lung cancer cell migration and invasion." (PMID 38188678, 2023). "CANTOS trial revealed IL-1β and inflammasome inhibition could significantly lower incidents of lung cancer." (PMID 36986550, 2023). "Additionally, incubating lung cancer cells with macrophages boosted the production of IL-1b and IL-6, which further encouraged the lung cancer cells to produce SAA1/2." (PMID 37444523, 2023). "Moreover, a signature of negative regulation of IL‐1β production was enriched in the ICB‐responded lung cancer patients in Gene Expression Omnibus datasets (GSE126044)." (PMID 37009412, 2023). "In preclinical models of KRAS-mutant lung cancer, the use of IL-1β inhibitors has been shown to reduce tumor burden, increase the infiltration of CD8+ T cells into the TME, elevate IFN-γ levels, decrease PD-1 expression, and reduce the number of exhausted PD-1+ T cells." (PMID 37511306, 2023). "Indeed, we found that expression of IL-1β, IL-6 and TNFα was dramatically reduced in lung cancer cells in response to BAY11-7082 treatment." (PMID 36457047, 2022). "And the inflammasome activation assay initially validated that NLRC4 could promote IL-1β maturation, which leads to pyroptosis of lung cancer." (PMID 36437954, 2022). "Additionally, secretion of IL-1β by lung cancer cells induces CD4+ T-cells to produce the tumor-promoting cytokine IL-22." (PMID 35086565, 2022). "Elsewhere, the inhibition of IL-1β by canakinumab significantly reduces the incidence and mortality of lung cancer as observed in a clinical trial, suggesting that pyroptosis may play distinct role in different cancers." (PMID 35774778, 2022). "Immunohistochemical analysis of human lung cancer specimens obtained from the two different groups of patients revealed that high CD68 expression levels in the peritumoral space correlated with strong positivity for IL-1β in patients with a poor prognosis." (PMID 35884397, 2022). "Recent data from the CANTOS trial highlighted a role for IL-1β in lung cancer development." (PMID 35086565, 2022). "Furthermore, previously reported data indicated that abnormal IL1B induction was related to poor prognostic outcomes in most malignant tumor types, including lung cancer, colon cancer, and BC." (PMID 36276158, 2022). "The reduction of lung cancer mortality in the CANTOS trial indicated that IL-1β-targeting therapy might also benefit patients with certain cancers." (PMID 36204568, 2022). "Taken together, these data suggest that targeting IL-1β plays a key role in reducing inflammation that could potentially promote the initiation and progression of lung cancer." (PMID 35086565, 2022). "The recent Canakinumab Anti-inflammatory Thrombosis Outcomes Study (CANTOS) trial evaluated the use of anti-interleukin-1β therapy in atherosclerotic disease; however, it also revealed interleukin-1β (IL-1β) blockade with canakinumab led to a significantly lower incidence of lung cancer." (PMID 35086565, 2022).
lung carcinoma (continued). "Previous studies revealed that IL-1β is a potent activator of the NF-κB pathway, and our group also demonstrated essential roles for NF-κB–mediated production of cytokines in the promotion of K-ras–mutant lung cancer in CC-LR mice." (PMID 35471938, 2022). "In addition, the levels of NLRP3, cleaved caspase-1, IL-1β and IL-18 were increased in the two lung cancer cells with miR-223-3p inhibition, and the corresponding results were contrary in miR-223-3p mimic group." (PMID 36276078, 2022). "In the IL family, IL-1β, IL-6, and IL-8 are cytokines with a wide range of biological activities, which are involved in the occurrence and metastasis of many kinds of tumors, lung cancer is one of them." (PMID 35928100, 2022). "In the Canakinumab Anti-inflammatory Thrombosis Outcomes Study (CANTOS), inhibition of the IL1β inflammatory pathway by Canakinumab has been shown to significantly reduce lung cancer incidence and mortality and similarly, administration of IL-1Ra reduced liver and lung metastasis." (PMID 35365751, 2022). "Besides, the levels of NLRP3, cleaved caspase-1, IL-1β and IL-18 were increased in the two lung cancer cells." (PMID 36276078, 2022). "Clinical outcomes of the CANTOS trial along with the ample in vitro and in vivo evidence of its role in tumor progression have led to the development of several clinical trials studying treatment of lung cancer based on anti-IL-1β therapy, either alone or in combination with anti-PD-1 therapy." (PMID 35086565, 2022). "Moreover, patients with certain cancers, especially lung cancer, can also benefit from IL-1β-targeting anti-inflammatory therapy." (PMID 36204568, 2022). "Indeed, IL-1β is abundant at tumor sites, including lung tumors; high levels of IL-1β were found in the serum and tissues of patients with lung cancer and correlated with poor prognosis." (PMID 35471938, 2022). "Lung cancer incidence and mortality might be reduced by IL-1β inhibition, but this is counterbalanced by the incidence of fatal infections and needs confirmation in other studies." (PMID 35406394, 2022). "In addition, toxicity of commercial CCL21 on MCF7 cells was similar to CCL21/IL1β recombinant protein, which is the anticancer antigen used for lung cancer treatment." (PMID 36037155, 2022). "Moreover, a previous study also reported that the level of IL-1β, IL-6, and TNF-α was notably up-regulated in lung cancer with Qi-yin deficiency." (PMID 35292015, 2022). "Patients treated with canakinumab had a lower risk of lung cancer incidence and mortality than those in the placebo group, suggesting that IL-1β might promote lung cancer initiation and/or progression." (PMID 36239242, 2022). "The results suggest that serum IL-1β, IL-6, and IL-8 are highly expressed in lung cancer, which might be considered potential biomarkers for lung cancer." (PMID 35928100, 2022). "This study retrospectively analyzed the level of serum CEA, IL-1β, IL-6, and IL-8 in patients with lung cancer, and the relationship between levels of these ILs with the pathological type and clinical stage of patients with lung cancer." (PMID 35928100, 2022). "In summary, our study suggests that serum IL-1β, IL-6, and IL-8 might serve as potential markers for the diagnosis of lung cancer." (PMID 35928100, 2022). "We further evaluated the value of CEA, IL-1β, IL-6, and IL-8 for the auxiliary diagnosis and prognostic evaluation of lung cancer, to provide more accurate potential molecular biomarkers for the diagnosis of the patient with lung cancer." (PMID 35928100, 2022). "The CANTOS trial suggests the role for IL-1β in lung cancer progression." (PMID 33686176, 2021). "Additionally, many other studies focus on role of innate immune system in carcinogenesis, confirmed importance of IL-1β in lung cancer development." (PMID 33658555, 2021).